EZH2 (enhancer of zeste 2 polycomb repressive complex 2 subunit)
Diseases named in the same sentence as EZH2 in open-access papers (continued):
Sharing a sentence is not in itself a finding about the gene and the disease.
ovarian carcinoma (continued). "Indeed, components of transcriptional repressors such as EZH2 which is required for transcriptional suppression of E2F6 is found to be low in normal ovarian cells and a sub-set of ovarian cancer." (PMID 25545504, 2014). "Inhibition of methyltransferase Repressive Complex 2 Subunit(EZH2)and acetyltransferase Histone Deacetylase(HDAC), which are involved in regulating histone modifications, can lead to tumor regression in AT-Rich Interaction Domain 1A (ARID1A) mutant ovarian cancer mouse models." (PMID 39445058, 2024). "Therefore, EZH2 has functions that result in the maintenance of ovarian cancer stem cells (CSCs) through effects on stemness and chemoresistance, with EZH2 functioning to induce CHK1 signaling to promote ovarian cancer chemoresistance." (PMID 37445833, 2023). "Further delineation of EZH2’s role in the cisplatin resistance of ovarian cancer has shown that EZH2 inhibition does not induce apoptosis, but it can suppress the cisplatin-resistant human ovarian cancer cell line SKOV3/DDP autophagy and reverse resistance to cisplatin." (PMID 36230683, 2022). "By contrast, in ovarian cancer models, Zou and colleagues found that EZH2 inhibition did not alter class I antigen presentation of ovarian cancer cells, which indicates that the regulation of EZH2 on antigen presentation may be cancer-type specific." (PMID 33403469, 2021). "Moreover, EZH2 in interaction with LINC00702, could suppress the transcription of KLF2 in ovarian cancer." (PMID 34462420, 2021). "Knockdown of EZH2 was able to re-sensitise the A2780-DDP cell line that is resistant to platinum through G2/M cycle arrest, which may have important implications for patients with platinum-resistant ovarian cancer." (PMID 33669182, 2021). "Another frequently reported target gene of miR-124 is the enhancer of zeste homolog 2 (EZH2), which has been found in lung adenocarcinoma, hepatocellular carcinoma cancer, cholangiocarcinoma, laryngeal squamous cell carcinoma, multiple myeloma, and ovarian cancer." (PMID 34072894, 2021). "The components of canonical and non-canonical EZH2 pathways were universally expressed in ovarian cancer specimens with a positive expression rate of 81.54% (53/65) for EZH2, 88.89% (48/54) for H3K27Me3, 63.07% (41/65) for pAkt1, and 75.38% (49/65) for pS21EZH2." (PMID 32435534, 2020). "Additionally we found EZH2 is highly expressed in the SKOV3 3rd cell line, a subline of SKOV3 with an expanded stem cell pool established by in vivo chemotherapy, and helped to maintain stemness and drug resistance of ovarian cancer stem cells." (PMID 33718109, 2020). "Moreover, we demonstrated that miR-138-5p could directly regulate the expression of EZH2 and SIRT1, which have been proven to be involved in regulation of cisplatin resistance of ovarian cancer." (PMID 32349783, 2020). "Surprisingly, in the ovarian cancer cells SKOV3, ChIP experiments showed that EZH2 could directly repress ZEB2 expression when EMT was induced in these cells following TGF-β treatment suggesting that EZH2 inhibited EMT in these cells." (PMID 34991274, 2018). "Interestingly, EZH2 has a similar functional spectrum to that of TIMP2 with regard to the regulation of tumor biology and plays an active role in metastasis and angiogenesis in ovarian cancer." (PMID 28620234, 2017). "Therefore, the oncogenic roles of both EZH2 and BMI1 and the implication of the lncRNAs/Polycomb axis with miRNAs show that lncRNAs and their functional protein partners are highly involved in the biology of ovarian cancer cells." (PMID 26992233, 2016). "Importantly, this is also consistent with the clinical evidence that the expression of E2F6 and c-KIT are correlated in ovarian cancer patients with low expression of EZH2 but not in cases of high EZH2 expression." (PMID 25545504, 2014).
ovarian carcinoma (continued). "Importantly, the results of ChIP assay showed that EZH2 could bind to P21 promoter region, and knockdown of LINC00511 expression could decrease EZH2’s binding to P21 promoter region and H3K27me3 modification in ovarian cancer cell." (PMID 31016892, 2019). "A related follow-up study showed that an EZH2 inhibitor sensitizes CARM1-high, but not CARM-low, HR-proficient epithelial ovarian cancer cells to PARP inhibitors." (PMID 37536629, 2023). "In all these ovarian cancer studies, CARM1 serves as a biomarker for cells amenable to EZH2 and/or PARP inhibition, rather than as a therapeutic target itself." (PMID 37536629, 2023). "Additionally, the DUF3518 domain of ARID1A was found to be functionally necessary to antagonize EZH2, and both the R1989* variant and the deletion of the DUF3518 domain could not rescue EZH2-mediated IFN-γ signaling gene repression in ARID1A-knockout ovarian cancer cells." (PMID 36371186, 2022).
glioblastoma (233 papers, 2010 to 2025). The most malignant astrocytic tumor (WHO grade IV). "The cellular lncRNA HOTAIR was described to interact with EZH2 in glioblastoma, thus linked to tumor dissemination, proneural-mesenchymal transition (PMT), and drug resistance." (PMID 38553638, 2024). "In glioblastoma, high expression of EZH2 has been associated with worse survival and high tumor grade." (PMID 38183103, 2024). "PTEN, an established target of EZH2, is downregulated in glioblastoma and associated with poor survival." (PMID 38183103, 2024). "To elucidate how PRMT6 enhances the invasion of glioblastoma cells, we first analyzed the previously completed proteomic data and found that the protein level of EZH2 was significantly down-regulated in PRMT6-deficient U87 cells." (PMID 39043634, 2024). "Circular EZH2 is highly expressed in glioblastoma cells and encodes EZH2-92aa, which binds MICA/B promoters to suppress their expression and also represses ULBP transcription via stabilizing EZH2." (PMID 38933287, 2023). "EZH2 cooperates with other oncogenes to accelerate myelodysplastic syndrome, and long-term suppression of EZH2 in glioblastoma causes a significant alteration in cell fate, ultimately leading to tumor progression." (PMID 38036730, 2023). "Consistent with our data, the cellular lncRNA HOTAIR was described to interact with EZH2 in glioblastoma, thus linked to tumor dissemination, PMT, and drug resistance." (PMID 37147437, 2023). "In another case, a protein encoded by circEZH2—EZH2-92aa, overexpressed in glioblastoma cells, induced the evasion of glioblastoma CSCs’ responses to NK cells." (PMID 36831219, 2023). "By catalyzing H3K27me3, EZH2 represses a series of tumor suppressor genes associated with the tumorigenic properties of glioblastoma, including CDKN1B, RUNX3, and HOXA5." (PMID 35927718, 2022). "The suppression of EZH2 in glioblastoma was shown to be associated with immune response, which induced changes in the secretion of immune cytokines." (PMID 34820775, 2022). "Though EZH2 inhibition has been approved by FDA for the treatment of a few cancer types, prolonged EZH2 depletion in glioblastoma even causes cell fate switch and results in tumour progression." (PMID 35851726, 2022). "EZH2 has been associated with stem cell properties and tumor-initiating cell function in different cancer types including glioblastoma, breast, and pancreatic cancers." (PMID 29921838, 2018). "Here, we found that oxygen consumption rates are reduced in glioblastoma cells depleted of EZH2, which suggests a deficiency in the TCA cycle." (PMID 27259264, 2016). "To investigate the effect of EZH2 on energetic transformation of glioblastomas, we separately introduced a pJAX vector encoding wild type EZH2 and a pSuper.neo vector encoding EZH2 shRNA into U251 and T98G glioblastoma cells." (PMID 27259264, 2016). "Inhibition of up-regulated EZH2 in angiogenic endothelial cells caused reduced migration, invasion, and tubule formation in vitro and diminished blood vessel formation in glioblastoma tumors in vivo." (PMID 21297974, 2011). "Two independent studies showed a highly significant association between EZH2 overexpression and poorer 1 year- and 3 year-survival in glioblastoma patients." (PMID 20920292, 2010). "Furthermore, the upregulation of EZH2 has been linked to advanced stages of lung, glioblastoma, and colorectal cancers, confirming its role in cancer aggressiveness and metastasis." (PMID 40038276, 2025). "pHGGs, including glioblastoma and DIPGs, and pediatric and juvenile HGGs are unique in that H3-K27M mutation occurs in more than half of cases, and the activity of EZH2 (histone-lysine N-methyltransferase Enhancer of zeste homolog 2) is suppressed by the H3-K27M mutation." (PMID 37700840, 2023). "EZH2 is commonly overexpressed in glioblastoma and is firmly associated with tumor malignancy." (PMID 35216113, 2022).
glioblastoma (continued). "Furthermore, we find that co-activation of NF-κB and EZH2 confers the poorest clinical outcome, and that the risk for glioblastoma can be accurately molecularly stratified by NF-κB and EZH2." (PMID 36263173, 2022). "For example, EZH2 was shown to contribute to glioblastoma-induced immune deficiency by exacerbating inflammation, and inhibition of EZH2 could reshape the immune function of microglia." (PMID 36552722, 2022). "It appears that EZH2 is up-regulated in a variety of human malignancies, including breast, colorectal, prostate, cervical and lung cancers, as well as sarcoma and glioblastoma, where its expression is associated with cancer initiation, progression, metastasis and prognosis." (PMID 27259264, 2016). "We recently found that overexpression of EZH2 was associated with poor outcome of glioblastoma (GBM)." (PMID 29228694, 2017). "In addition, upregulation of EZH2 has been linked to glioblastomas." (PMID 24367637, 2013). "For instance, EZH2 enhances STAT3 activity by increasing STAT3 tyrosine phosphorylation in glioblastoma." (PMID 39636550, 2025). "In the context of glioblastoma, the EZH2/H3K27Me3/DNMT1 complex orchestrates the methylation of the AP-2α gene, inhibiting its transcriptional activity." (PMID 40675967, 2025). "Recently, we demonstrated synergistic antitumor effects of the CDK4/6 inhibitor abemaciclib and the EZH2 inhibitors GSK126 or tazemetostat in patient-derived glioblastoma (GBM) models." (PMID 40284428, 2025). "In glioblastoma, EZH2 promotes the expression of ATP-binding cassette transporter multi-drug resistance, multi-drug resistance-associated protein, and breast cancer resistance protein to strengthen chemoresistance." (PMID 40028035, 2025). "Our findings demonstrate that PRMT6 is capable of facilitating the post-translational modification of EZH2 in glioblastoma cells." (PMID 39043634, 2024). "Further mechanistic investigations found that PRMT6 inhibits the transcription of TRAF6 by activating the histone methylation mark (H3R2me2a), and reducing the interaction between TRAF6 and EZH2 to enhance the protein stability of EZH2 in glioblastoma cells." (PMID 39043634, 2024). "Once EZH2 is activated via phosphorylation in glioblastoma, it proceeds to methylate a downstream target, NFĸB." (PMID 38183103, 2024). "EZH2 was found to activate aerobic glycolysis in glioblastomas, esophageal cancer, and prostate cancer cells to promote tumorigenesis and progression." (PMID 37992808, 2024). "Nevertheless, we should also recognize several limitations, among which EZH2 has been revealed to drive the malignant progression of glioblastoma by acting on downstream molecules." (PMID 39043634, 2024). "EZH2’s cellular interplay with E2F transcription factors in glioblastoma models is one mechanism that offers tumor cell proliferation and growth." (PMID 38183103, 2024). "Then, western blotting revealed that inhibition of TRAF6 expression in glioblastoma cells promoted the upregulation of EZH2 protein levels, while increased expression of TRAF6 had the opposite effect." (PMID 39043634, 2024). "Our findings illustrate that PRMT6 suppresses TRAF6 transcription via H3R2me2a to enhance the protein stability of EZH2 to facilitate glioblastoma cell invasion and migration." (PMID 39043634, 2024). "For example, the m6A methyltransferase METTL3 mediates the expression of a histone modifier EZH2 in an m6A‐dependent manner under temozolomide treatment in glioblastoma." (PMID 38773866, 2024). "Based on the proposed role of EZH2 in glioblastoma, inhibition of this writer has triggered interest as a therapeutic target." (PMID 38183103, 2024). "NFĸB methylation mediates the effect of EZH2 to induce glioblastoma proliferation and maintenance of stem-like characteristics." (PMID 38183103, 2024). "Wound healing assays also showed that re-expression of EZH2 rescued the inhibition of glioblastoma cell migration ability by PRMT6 silencing." (PMID 39043634, 2024).
glioblastoma (continued). "Overall, E2F7 is responsible, in part, for the proliferative advantages in glioblastoma mediated by EZH2 inhibition of PTEN and leading to activation of the PI3K/AKT/mTOR pathway." (PMID 38183103, 2024). "To investigate the role of EZH2 in PRMT6-mediated glioblastoma cell invasion and migration, we transfected the EZH2 ORF plasmid into PRMT6-silenced glioblastoma cells to re-expressed EZH2 to construct a rescue cell model." (PMID 39043634, 2024). "EZH2 interacts with maternal embryonic leucine-zipper kinases (MELK) in glioblastoma and medulloblastoma." (PMID 38183103, 2024). "This axis’ activation was notably detected in CMV-transformed HMECs (CTH), CMV-transformed OECs (CTO cells), and CMV-elicited glioblastoma cells (CEGBCs) exhibiting a significant increase in Myc and EZH2 proteins." (PMID 38534385, 2024). "To determine the role of TRAF6 in regulating EZH2 protein homeostasis in glioblastoma cells, we performed Co-IP experiments in U87, LN229, and HEK293T cells." (PMID 39043634, 2024). "Single-cell RNA-seq of patient-derived glioblastoma cells revealed the presence of a subpopulation of cells with high EZH2 expression that correlated with poor patient survival." (PMID 39409910, 2024). "Then, we identified that PRMT6 maintains the protein stability of EZH2 by inhibiting the degradation of EZH2 protein, thereby mediating the invasion and migration of glioblastoma cells." (PMID 39043634, 2024). "The protein expression of EZH2 in MG132-treated TRAF6-silenced glioblastoma cells was investigated, and western blotting results showed that EZH2 protein levels were further up-regulated compared with TRAF6-silenced glioblastoma cells." (PMID 39043634, 2024). "Transwell assays revealed that PRMT6 silencing significantly attenuated the invasion of LN229 and U87 cells, while EZH2 overexpression restored the invasive ability of PRMT6-silenced glioblastoma cells." (PMID 39043634, 2024). "Our results demonstrate that TRAF6 interacts with EZH2, facilitating its ubiquitination and subsequent degradation in glioblastoma cells, in line with existing research." (PMID 39043634, 2024). "In glioblastoma, silencing EZH2 with siRNA resulted in a decline in fatty acid synthase levels, which was accompanied by lower fatty acid levels." (PMID 37992808, 2024). "Throughout our study, we identified that TRAF6 is a regulator of EZH2 stability through ubiquitination in glioblastoma cells." (PMID 39043634, 2024). "To further assess the effect of TRAF6 on EZH2 protein stability, we examined EZH2 abundance in TRAF6-depleted glioblastoma cells or TRAF6-overexpressed HEK293T cells treated with CHX." (PMID 39043634, 2024). "Highlighting the critical role of EZH2 and HCMV in our glioblastoma model, the impact of EZH2 inhibitor (GSK343) and anti-HCMV drug ganciclovir (GCV) alone and in combination with TMZ was assessed." (PMID 37147437, 2023). "A functional approach showed that stable knockdown of EZH2-92aa enhances NK cell-mediated glioblastoma CSCs eradication in vitro and in vivo, synergizing with anti-PD1 therapy." (PMID 36831219, 2023). "EZH2 is involved in glioblastoma-induced immunosuppression, it induces IL-10 as well as TGF-β secretion in glioblastoma cells and attenuates microglia phagocytosis and shifts toward the M2 phenotype." (PMID 37700840, 2023). "Recent studies in glioblastoma and bladder carcinoma confirm the interaction of H19 with enhancer of zeste homolog 2 (EZH2) regulation." (PMID 36960964, 2023). "Taken together, we identify a key axis from the canonical NF-κB pathway to the EZH2 signaling, linking chronic inflammation and epigenetic reprogramming and promoting the malignant progression of glioblastoma." (PMID 36263173, 2022). "The results revealed that p65 regulates the EZH2 promoter via the -488bp/-479bp region in glioblastoma cells." (PMID 36263173, 2022).